NF1 (neurofibromin 1)
Diseases named in the same sentence as NF1 in open-access papers (continued):
Sharing a sentence is not in itself a finding about the gene and the disease.
melanoma (continued). "In this paper, we report an oral melanoma occurring in a patient with NF1 disorder, diagnosed at a locally advanced stage, successfully managed by definitive external beam radiotherapy, along with a comprehensive literature review on the melanoma-NF1 association." (PMID 35761911, 2022). "Indeed, RASA2- and NF1-mutated genes co-selection in melanoma could be equivalent to oncogenic RAS mutation." (PMID 32850962, 2020). "Future studies could also take into consideration NF-1 mutations, which are identified in roughly 10% of metastatic cutaneous melanoma or other genomic markers, the predictive role of which, in the management of stage IV melanoma, may arise in the future." (PMID 33105692, 2020). "Importantly, NF1 mutations have been found in melanomas that lack both BRAF and NRAS mutations, with 25–30% of such melanomas found to harbour deleterious NF1 mutations, thus implying that NF1 inactivation has conferred aberrant MAPK pathway activation in these tumours." (PMID 28637487, 2017). "Importantly, we found NF1‐mutated melanomas to harbor distinct biological characteristics and to be associated with poor survival outcome, suggesting that further characterization of these melanomas is required." (PMID 28267273, 2017). "NF1 mutational loss in desmoplastic melanoma is often associated with concurrent mutations in RASopathy genes; these concurrent mutations may act synergistically in melanoma development." (PMID 29156643, 2017). "Nine of the 37 NF1-associated melanoma cases reported in the literature were associated with giant congenital melanocytic nevi which supports the hypothesis that nevi might be the primary source of NF1-associated melanomas." (PMID 16961930, 2006). "Rarely, ocular, cutaneous or anorectal malignant melanomas may be identified in patients with NF-1, This rare association has caused controversy as to whether patients with NF-1 have an inherently higher risk for melanomas or whether the associations can be explained by chance alone." (PMID 15363097, 2004). "Melanoma is the most aggressive skin malignant tumor, typically exhibiting a high mutation burden and potentially harboring mutations in NRAS, BRAF, or NF1." (PMID 41492362, 2026). "Compared with other studies of melanoma, we found fewer mutations in classical driver genes such as BRAF, NRAS or NF1." (PMID 41708869, 2026). "Inhibitors of the PI3K/mTOR pathway and cell cycle are also promising for NF1‐mutant melanoma, as discussed in Section 3.3." (PMID 41492362, 2026). "The increased invasion and metastasis of melanoma cells are linked to mutations in BRAF, NRAS, and NF1 genes." (PMID 42193039, 2026). "explored the combining of HDAC inhibitors (entinostat) with BRAF/MEK inhibitors in melanoma cells harboring BRAF, NRAS, PTEN, or NF1 mutations." (PMID 41492362, 2026). "Given that NF1 mutations primarily enhance RAS/MAPK signaling, therapeutic inhibition of this pathway is a rationally supported strategy for NF1‐mutant melanoma." (PMID 41492362, 2026). "NF1‐mutant melanomas are clustered within elderly individuals and chronically sun‐exposed skin, and they exhibit a distinctive molecular profile marked by high mutation burden and the absence of BRAF or NRAS mutations." (PMID 41492362, 2026). "The genes most frequently associated with melanoma pathogenesis include BRAF, NRAS, neurofibromin 1 (NF1), and KIT." (PMID 39859576, 2025). "Melanotic melanoma cells often retain functional melanogenesis pathways and carry mutations commonly found in cutaneous melanoma, such as BRAF V600E, NRAS or NF1." (PMID 40649764, 2025). "In the intradermal melanomas, there were 15 upregulated genes and 10 downregulated genes in the Nf1flox/+ tumors compared with Nf1 +/+, with Padj <0.05." (PMID 39804140, 2025).
melanoma (continued). "Typically, NF1 and NRAS mutations are considered mutually exclusive in melanomas, as both affect the RAS/MAPK pathway." (PMID 40125165, 2025). "Accurate diagnosis of dedifferentiated melanoma demands a high level of suspicion and comprehensive sampling to identify either a conventional melanoma precursor or mutations consistent with melanoma, such as BRAF, NRAS, or NF1." (PMID 39625060, 2025). "We included 7 intradermal melanomas (3 Nf1 +/+ and 4 Nf1flox/+), 4 sparse pigment tumors (all Nf1flox/+), and 10 uveal melanomas (5 Nf1 +/+ and 5 Nf1flox/+)." (PMID 39804140, 2025). "Accordingly, the author believes that a large-scale study of the latter population would reveal the relationship between melanoma and NF1; however, such a study has yet to be performed." (PMID 40153767, 2025). "Our findings on MITF and NF1 further suggest that certain COM subtypes share mechanisms with human melanomas." (PMID 40647405, 2025). "Mutations common in melanoma, including BRAF, NRAS, and NF1 activate downstream signaling via the mitogen-activated protein kinase (MAPK) pathway and are more commonly found in non-ALM." (PMID 39941835, 2025). "The ratio of intradermal melanomas to sparse pigment tumors was similar in Nf1 +/+ and Nf1flox/+ genotypes, and both types were found in males and females." (PMID 39804140, 2025). "Although trametinib is known to be highly effective against BRAF/NRAS wild-type melanoma, its sensitivity in NF1-negative melanoma cell lines is comparable to that in NF1-expressing lines, suggesting that further research is required." (PMID 41001300, 2025). "Molecular profiling confirmed the diagnosis of melanoma and identified mutations in the TERT promoter, NRAS, NF1, PBRM1, FAT1, and ATM genes." (PMID 40125165, 2025). "On one hand, common genetic mutations in melanoma, such as BRAF, NRAS, and NF1, result in multiple potential resistance pathways within the MAPK signaling axis." (PMID 40599859, 2025). "In conclusion, our study revealed that actionable gene alterations in BRAF, NRAS, KIT, and NF1 are common in Japanese patients with melanomas." (PMID 39823560, 2025). "Numerous research efforts are currently focused on developing targeted therapies for melanomas driven by NRAS mutations, NF1 loss-of-function mutations, and other genetic alterations that activate the MAP kinase pathway." (PMID 40867277, 2025). "Tovorafenib resulted in tumor regression in an AGK::BRAF fusion melanoma patient-derived xenograft model in vivo, while exhibiting little antitumor activity in NF1-LOF tumor models." (PMID 40111124, 2025). "Nf1flox/+ mice also lost weight more quickly than Nf1+/+ mice, which is consistent with accelerated intradermal melanoma development." (PMID 39804140, 2025). "(2012) identified BRAF mutations in 50% of melanomas, NRAS mutations in 30%, NF1 mutations in 12–23%, and PTEN mutations in 5–40%, highlighting their role in melanoma progression and therapeutic responsiveness." (PMID 41142596, 2025). "In melanomas, Class I MAP2K1 mutations have been identified as secondary oncogenic drivers, typically occurring alongside BRAF, NRAS, or NF1 mutations." (PMID 40107205, 2025). "The Neurofibromin 1 (NF1) gene is frequently somatically mutated in melanoma, and pathogenic germline variants in this gene are a known risk factor for melanoma, in addition to neurofibromatosis." (PMID 40072281, 2025).
melanoma (continued). "Based on prevalent mutational patterns, melanoma can be classified into four subtypes: mutant BRAF, mutant RAS, mutant NF1, and Triple-WT (wild type), with BRAF or RAS mutations being the most common drivers of melanoma development." (PMID 40331942, 2025). "The MAPK pathway has a crucial role in melanoma pathogenesis and is activated by mutations in the key signalling pathway members, including BRAF, NRAS, NF1 and KIT." (PMID 41017066, 2025). "Loss of PTEN and NF1 tumor suppressors, as well as UVR, cooperates with BRAFV600E in melanoma development and progression." (PMID 39115053, 2025). "Approximately 85% of melanomas harbor primary pathogenic alterations in key genes such as BRAF, NRAS, NF1 or KIT, which include mutations, deletions or amplifications." (PMID 39859576, 2025). "Mutations in BRAF, NRAS, NF1, and KIT drive overactivation of the Ras/RAF/MAPK/ERK and PI3K/AKT/mTOR signaling pathways, promoting melanoma progression." (PMID 39941158, 2025). "Ideally, the role of Nf1 in melanoma would be studied separately in mice with only uveal melanoma or only intradermal melanoma." (PMID 39804140, 2025). "Similar to findings in White melanoma studies, variants in BRAF (25%), NRAS (20%), NF1 (17%), and KIT (17%) were prevalent in Japanese melanomas (Appendix Fig A1B)." (PMID 39823560, 2025). "The molecular development of melanoma is mainly associated with mutations in the v-Raf (BRAF), NF-1 (neurofibromin 1), NRAS (neuroblastoma RAS viral oncogene homolog), and MC1R (melanocortin 1 receptor) genes." (PMID 40710294, 2025). "MEK inhibitors (MEKi) were shown to be clinically insufficiently effective in patients suffering from BRAF wild-type (BRAF WT) melanoma, even if the MAPK pathway was constitutively activated due to mutations in NRAS or NF-1." (PMID 38263136, 2024). "RAC1 mutations are insufficient to drive melanoma and are almost always found with other activating MAP kinase hot spot mutations, most frequently NRAS (47%), BRAF, or NF1." (PMID 40396280, 2024). "Targeting NF1-regulated pathways such as RAS/MAPK or PI3K/mTOR offers potential therapeutic options for patients with melanoma." (PMID 38565978, 2024). "Melanomas fall into 4 genomic categories based on driver mutations: BRAF (50%), NRAS (25%), or NF1 (15%) mutant and triple WT." (PMID 38319712, 2024). "Current treatments of NF1-mutant melanomas rely on targeting other proteins, such as MEK and anti-PD-1 therapy." (PMID 38732242, 2024). "The Cancer Genome Atlas has proposed a genetic classification of melanoma into four subtypes based on mutations in BRAF, NRAS, NF1 and triple-wild-type melanomas." (PMID 38903495, 2024). "In melanomas, the hyperactivation of the MAPK pathway is mainly through activating mutations in BRAF, NRAS, NF1, and KIT." (PMID 38247727, 2024). "BRAF and NRAS mutant melanomas histopathologically correlate with low cumulative sun damage (low-CSD) melanomas, while NF1 mutant melanomas are classified as high-CSD." (PMID 38611025, 2024). "RAC1 mutations are present in 2–9% melanomas, usually in association with activation mutations in BRAF or NRAS, or inactivating mutations in NF1." (PMID 40396280, 2024). "NF1-mutant melanomas in our cohort were enriched for SV events affecting SPRED1 and RAF1, the latter of which has been implicated in activating fusion events in cutaneous melanoma and was observed to be enriched in TWT tumors." (PMID 38758740, 2024). "A study of whole-genome sequences from cutaneous, acral, and mucosal subtypes of melanoma in 183 melanoma samples found that BRAF, NRAS, and NF1 were significantly mutated genes in AM, while SF3B1 (splicing factor 3B subunit 1) was identified in MM." (PMID 38469235, 2024). "The frequency of RAS and NF1 mutations varies depending on the tumor tissue of origin: in melanoma, due to the lower endogenous baseline RAS activity, class III BRAF mutations almost always coexist with mutated RAS or NF1." (PMID 39529955, 2024).
melanoma (continued). "NF1 + melanomas constitute about 12–23% of melanoma patients and are characterized by the highest mean rate of mutations (39 mutations/MB), stronger than BRAF + subtype UV signature correlation, and worst overall survival." (PMID 39340537, 2024). "Given that NF1 loss and overactivation of RAS signaling drives tumorigenesis in these contexts, it would be expected that more patients with NF1 would develop melanoma, along with other Ras-driven malignancies." (PMID 39687068, 2024). "Although so far, only BRAF is targetable, the establishment of NRAS and NF1 status is important as it will allow further research on the influence of these genes on the clinical behavior of melanoma." (PMID 39340537, 2024). "RAF inhibitors such as dabrafinib have been shown to be effective in BRAF-mutant melanomas; however, in BRAF-mutant melanomas with concurrent NF1 mutations, RAF inhibitors are less effective due to remaining hyperactive RAS signaling." (PMID 39016685, 2024). "One tumor with an NRAS G12R mutation had an intrachromosomal chromothripsis event spanning KRAS, while BRAF and NF1 were involved in chromothripsis events in one NRAS melanoma each." (PMID 38758740, 2024). "NF1-mutant melanomas preferentially harbored alterations in RASopathy genes, with SPRED1, RASA2, and RASSF2 being identified as significantly mutated genes within the subtype." (PMID 38758740, 2024). "The distribution of small INVs observed in NF1-mutant melanomas was largely driven by 2 samples, both of which had chromothripsis." (PMID 38758740, 2024). "Analysis of the BRAF, NRAS, and NF1 genes in patient samples will allow for the classification of melanoma into four proposed molecular subtypes." (PMID 39340537, 2024). "successfully created several zebrafish ‘Fin’ melanoma systems that are driven by genes such as CRKL, GAB2 and NF1, analogous to human melanomas that lack BRAF/KIT/NRAS alterations." (PMID 39627834, 2024). "In detail, about 50% of melanomas are BRAF mutations (principally mutations at the V600 codon), around 30% are RAS mutations, 10–15% are NF1 mutations, and about 5–10% are triple wild-type mutations." (PMID 39334716, 2024). "The known genetic drivers of melanoma include B-raf proto-oncogene (BRAF), neurofibromin 1 (NF1), and NRAS mutations." (PMID 38399429, 2024). "Mutations in BRAF, NRAS, NF1, and CKIT are sometimes referred to as “driver” mutations, as they rarely overlap each other in melanoma cells." (PMID 38339344, 2024). "A method has been proposed to increase sensitivity to trametinib in melanoma cell lines by stabilizing the NF1 protein by lowering its degradation." (PMID 38534309, 2024). "All but one (88%) NF1-mutant melanomas that harbored chromothripsis involved interchromosomal SVs, compared with just 38% of BRAF-mutant melanomas with chromothripsis." (PMID 38758740, 2024). "Loss of NF1 also occurs in sporadic tumors, such as glioblastoma (GBM), melanoma, breast, ovarian and lung cancers." (PMID 39016685, 2024). "Previous genomic classification of melanoma patient based on the pattern of the most prevalent significantly mutated genes leads to four subtypes, including mutant BRAF, mutant RAS, mutant NF1, and Triple-WT (wild-type)." (PMID 37904237, 2023). "In the NF1 cohort, 15 patients were diagnosed with melanoma (0.9%), which is over three times higher than the prevalence in the general population (0.24%)." (PMID 37345107, 2023). "Approximately 9–21.9% acral melanomas have NRAS mutations and 11–23% acral melanomas harbor NF1 mutations." (PMID 37239381, 2023).
melanoma (continued). "Regarding the prevalent melanoma-related mutated genes BRAF, NRAS and NF1, 38 known oncogenic mutations were found in all 46 melanoma samples." (PMID 36765773, 2023). "This mutation scenario was also proven in our cohort, with melanomas in face and scalp mostly carrying BRAF V600K, NRAS and NF1 mutations, whereas only one out of eight patients (12.5%) carried the BRAF V600E mutation." (PMID 36765773, 2023). "Several clinical trials have demonstrated the benefits of MEK inhibitors (e.g., trametinib, cobimetinib, mirdametinib and selumetinib in melanoma and NF1." (PMID 36755948, 2023). "Somatic NF1 mutations often co-occur with other genetic alterations, particularly BRAF and NRAS mutations, which are common in melanoma." (PMID 37504268, 2023). "Other somatic mutations have also since been identified in melanomas including TERT, NRAS, NF1, and KIT in approximately 70-85%, 20-30%, 10-15, and 10% of melanomas, respectively." (PMID 37841001, 2023). "Triple wildtype (TWT) melanomas that lack mutations in BRAF, NRAS, or NF1 form 10% of human melanomas and are heterogeneous in their genomic drivers." (PMID 36901951, 2023). "Given the increased risk of melanoma and NMSC in patients with NF1, consensus screening guidelines are needed in order to promote early skin cancer detection in this high-risk population." (PMID 37345107, 2023). "The relevance of this pathway is underlined by the fact that hyperactivity of the ERKs through mutations in NRAS, its negative regulator NF1, or its downstream effector BRAF are causally related to ~75% of sporadic melanomas." (PMID 37762683, 2023). "Numerous efforts are underway to target melanomas with NRAS mutations, NF-1 LOF mutations, and other genetic alterations leading to activation of the MAP kinase pathway." (PMID 37370834, 2023). "Both IL-17 and TH17 cell differentiation GES were among the most significantly over-represented pathways in MAPK-mutated (n = 77 BRAF hotspot-mutant, n = 42 NRAS hotspot-mutant, n = 1 NF1-mutant) melanomas compared to triple-WT melanomas (n = 36)." (PMID 37525015, 2023). "Class 3 BRAF mutations and NF1 loss were common in various HRAS-mutant cancers, in particular melanomas." (PMID 37503077, 2023). "Higher percentages of BRAF, RAS, NF1, and CBL mutations were observed in patients with melanoma in the head and neck than in patients with melanoma in the other five sites." (PMID 37649078, 2023). "As the mitogen-activated protein kinase (BRAF-MAPK) signaling pathway is frequently activated in melanoma, we analyzed TERT in melanoma subtypes with hotspot mutations in BRAF, RAS (NRAS, KRAS, HRAS) and NF1 genes in the SKCM cohort." (PMID 37418389, 2023). "The activity of selumetinib against not only NF-1-related PN, but also several cancers (including thyroid cancer, lung cancer and melanoma) has been observed, and selumetinib has been studied in children and adults with NF1-related PN." (PMID 37400844, 2023). "According to the four main melanoma genetic subtypes established by The Cancer Genome Atlas (TCGA), we found 52.8% (19/36) BRAF-mutant, 30.6% (11/36) NRAS-mutant, 8.3% NF1-mutant, and 13.9% (5/36) triple wild-type melanomas." (PMID 36901733, 2023). "As a tumor suppressor protein, NF1 is also somatically inactivated in multiple malignancies, including melanoma." (PMID 37345107, 2023). "In melanoma, SNVs in NF1 were more frequent in tumours of older individuals, while BRAF SNVs were more frequent in tumours of younger individuals." (PMID 35017538, 2022).